SNHG14 (small nucleolar RNA host gene 14)
Synonyms: NCRNA00214; UBE3A-AS; UBE3A-ATS; formerly UBE3A-AS1; IPW
Gene: Long non-coding RNA gene on chromosome 15 (24,978,583 to 25,420,336, forward strand). Ensembl gene ENSG00000224078.
Gene Ontology:
Biological process: RNA processing
Cellular component: nucleolus
Diseases named in the same sentence as SNHG14 in open-access papers:
SNHG14 is named in the same sentence as 64 diseases in open-access papers, as found by Europe PMC text mining. Sharing a sentence is not in itself a finding about the gene and the disease. The quoted sentences say what the papers report.
breast carcinoma (14 papers, 2018 to 2022). "RT‐qPCR assay showed that SNHG14 was up‐regulated in breast cancer tissues and associated with trastuzumab response." (PMID 30063126, 2018). "Based on the up‐regulation model of SNHG14 in breast cancer, we investigated the diagnostic potential of SNHG14 in differentiating breast cancer patients from healthy group." (PMID 30063126, 2018). "Taken together, our clinical data indicate that SNHG14 may be a promising diagnostic marker for breast cancer patients." (PMID 30063126, 2018). "Currently, however, the expression pattern, biological function and underlying mechanism of SNHG14 in breast cancer progression and trastuzumab resistance are largely unknown." (PMID 30063126, 2018). "Furthermore, the expression level of SNHG14 in circulating EVs was increased in patients who exhibited resistance to trastuzumab, compared with those exhibiting a response, suggesting lncRNA-SNHG14 in serum vesicles as a potential diagnostic biomarker for breast cancer." (PMID 33800302, 2021). "Therefore, SNHG14 may serve as a novel diagnostic and therapeutic target for breast cancer patients." (PMID 30063126, 2018). "Therefore, SNHG14 could be considered as a promising diagnostic biomarker and therapeutic target for breast cancer patients, enhancing the clinical benefits of trastuzumab therapy." (PMID 30063126, 2018). "Curiously, the transfer of lncRNA small nucleolar RNA host gene 14 (SNHG14) by EVs shed by trastruzumab-resistant HER2+ breast cancer cells has also been reported to be a resistance mechanism to this antibody." (PMID 32384712, 2020). "Similar regulatory mechanisms have also been identified, wherein lncRNA SNHG14 binds to miR-193a-3p in breast cancer, and silencing of lncRNA SNHG14 up-regulates miR-193a-3p to inhibit the growth and invasion of breast cancer cells." (PMID 31660971, 2019). "To further investigate how SNHG14 functions in breast cancer cells, we determined the downstream targeted genes by conducting RNA‐pull down experiments followed by mass spectrometry." (PMID 30063126, 2018). "To this end, we validated that the Nrf2 pathway is responsible for the SNHG14/PABPC1‐induced breast cancer progression." (PMID 30063126, 2018). "A significant elevated expression of SNHG14 was identified in breast cancer tissues when compared to matched non‐tumour tissues." (PMID 30063126, 2018). "As expected, we confirmed that PABPC1 was essential for SNHG14‐induced breast cancer tumorigenesis and trastuzumab resistance." (PMID 30063126, 2018). "Collectively, we draw a conclusion that lncRNA SNHG14 regulates PABPC1 expression in breast cancer via modulation of H3K27 acetylation at promoter of PABPC1." (PMID 30063126, 2018). "In this study, we has been suggested that lncRNA SNHG14 regulated breast cancer progression and resistance via regulating PABPC1 expression through H3K27 acetylation." (PMID 30063126, 2018). "We then investigated the functional role of SNHG14 in breast cancer progression and trastuzumab resistance using two HER2+ cell lines, SKBR‐3 and BT474." (PMID 30063126, 2018). "In this study, we identified the expression level and functional role of SNHG14 in breast cancer progression and trastuzumab resistance." (PMID 30063126, 2018). "The roles of lncRNAs in breast cancer progression have long been researched and SNHG14 was identified as an oncogene." (PMID 30063126, 2018). "We then identified the expression level of SNHG14 in breast cancer cells and found that SNHG14 was up‐regulated in six breast cancer cells when compared to normal breast epithelium MCF‐10A cells." (PMID 30063126, 2018). "By performing in vitro and in vivo experimental assays, we further investigated the functional relevance of SNHG14 with breast cancer progression." (PMID 30063126, 2018). "Our own date showed that SNHG14 promoted breast cancer tumorigenesis and chemo‐resistance via activating PABPC1 through H3K27 acetylation." (PMID 30063126, 2018).
breast carcinoma (continued). "Interestingly, in breast cancer, exosomal lncRNA small nucleolar RNA host gene 14 (SNHG14) mediates resistance to trastuzumab, the monoclonal antibody used in its treatment." (PMID 35966579, 2022). "To investigate whether the expression of SNHG14 is altered in breast cancer, we detected the expression of SNHG14 in 36 breast cancer tissues and paired adjacent non‐tumour tissues." (PMID 30063126, 2018). "In addition, 61.1% (22 of 36) cases showed more than 2‐fold higher level of SNHG14 in breast cancer tissues in contrast to paired normal tissues." (PMID 30063126, 2018). "To this end, we demonstrated that SNHG14 played an oncogenic role in breast cancer progression." (PMID 30063126, 2018). "To verify this hypothesis, we determined the expression level of SNHG14 in breast cancer tissues and cell lines." (PMID 30063126, 2018). "Next, transwell assay also showed that SNHG14 promoted breast cancer cell invasion." (PMID 30063126, 2018). "According to the expression of SNHG14 in breast cancer cells, among which SKBR‐3 showed the highest level while BT474 indicating a lowest endogenous expression, we constructed SNHG14 overexpression model using BT474 cells and SNHG14 knockdown model using SKBR‐3 cells." (PMID 30063126, 2018). "Overexpression of SNHG14 promoted the level of PABPC1 in either 1% Tween‐80 or trastuzumab treatment group (Group II vs Group I or Group III vs Group IV, respectively), indicating that SNHG14 regulates breast cancer carcinogenesis and trastuzumab resistance via targeting PABPC1." (PMID 30063126, 2018). "These contradictory conclusions lead us to identify the function of SNHG14 in breast cancer." (PMID 30063126, 2018). "To further investigate whether lncRNA SNHG14 regulates the H3K27 acetylation at PABPC1 promoter, we sublocated the expression of SNHG14 in breast cancer cells." (PMID 30063126, 2018). "Moreover, this histone acetylation was mediated by SNHG14 as evidenced by the changed enrichment induced by overexpression or knockdown of SNHG14 in breast cancer cells." (PMID 30063126, 2018). "Finally, a trio of lncRNAs have been found to regulate trastuzumab resistance in Human Epidermal Growth Factor Receptor positive (HER2+) breast cancer cells, including Actin Filament Associated Protein 1 Antisense RNA1 (AFAP1-AS1), AGAP2-AS1, and small nucleolar RNA host gene 14 (SNHG14)." (PMID 33920605, 2021). "Thus, SNHG14 may serve as a promising target for patients with HER2-positive breast cancer." (PMID 34631721, 2021). "To determine the expression of SNHG14 in trastuzumab‐treated patients, we collected 62 cancer tissues from advanced HER2+ breast cancer patients who received single trastuzumab treatment." (PMID 30063126, 2018). "In breast cancer, studies have indicated that PABPC1 mediates SNHG14-induced oncogenic effects." (PMID 34151731, 2021). "For instance, trastuzumab resistance has been reported in breast cancer by AGAP2-AS1 and SNHG14, whereas UCA1 was responsible for tamoxifen resistance in breast cancer, cisplatin resistance in ovarian cancer, and cetuximab resistance in metastatic colorectal cancer." (PMID 34067896, 2021). "A recent study illustrated that SNHG14 promotes proliferation, invasion, and trastuzumab resistance via modulating poly(A) binding protein cytoplasmic 1 (PABPC1) expression through H3K27 acetylation in breast cancer cells." (PMID 32811821, 2020). "To determine the signalling pathway that directly involved in breast cancer progression and chemo‐resistance, we used Signal Reporter Array to simultaneously investigate the activity changes of canonical signalling pathways in BT474 cells upon overexpression of SNHG14." (PMID 30063126, 2018).
colorectal cancer (14 papers, 2020 to 2026). A primary or metastatic malignant neoplasm that affects the colon or rectum. "Beyond its established oncogenic roles in cancers such as hepatocellular carcinoma, pancreatic cancer, and colorectal cancer, SNHG14 has recently been implicated in cardiac pathology." (PMID 41602333, 2026). "Wang's study demonstrated that SNHG14 enables the proliferation and invasion of colorectal cancer cells by mediating the miR‐519b‐3p/DDX5 axis." (PMID 40521987, 2025). "In colorectal cancer, SNHG14 modulates the miR-519b-3p/DDX5 axis to promote cell proliferation and invasion." (PMID 40561678, 2025). "Overexpression of SNHG14 promoted colorectal cancer cell proliferation, invasion, and migration and epithelial-mesenchymal transition in vitro and enhanced tumor growth and distant metastasis in vivo." (PMID 34631721, 2021). "However, the underlying molecular mechanism of SNHG14 in colorectal cancer (CRC) remains unclear." (PMID 34234865, 2021). "Recently, it is reported that high expression of SNHG14 in tumor tissue promotes cancer cell invasion and metastasis by targeting hsa-mir-145 in gastric cancer and hsa-mir-944 in colorectal cancer." (PMID 33552958, 2020). "MiR‐32‐5p also presents low expression and involve in the ceRNA axis of SNHG14/miR‐32‐5p/SKIL in colorectal cancer." (PMID 33448691, 2020). "Thus, further studies are still needed before determining conclusions related to the function and regulatory mechanisms of SNHG14 in colorectal cancer." (PMID 34631721, 2021). "Furthermore, mechanistic investigations demonstrated that SNHG14 facilitates colorectal cancer progression by targeting EZH2-regulated EPHA7 and absorbing miR-186-5p." (PMID 34631721, 2021). "Finally, we found that SNHG14 promotes cell proliferation and invasion in colorectal cancer through modulating miR-519b-3p/DDX5 axis." (PMID 34234865, 2021). "In colorectal cancer biopsies, high expression of SNHG14 and ATG14 was observed." (PMID 33117715, 2020). "For example, in colorectal cancer, the upregulation of small nucleolar RNA host gene 14 (SNHG 14) suppresses the progression and metastasis of colorectal cancer cells by competing with miR-92b-3p." (PMID 34380511, 2021). "In the same work, SNHG14 inhibited miR-186, which blocked ATG14 expression in cisplatin-resistant colorectal cancer cell lines." (PMID 33117715, 2020). "Although it was widely reported that SNHG14 served as an oncogene in various cancers including hepatocellular carcinoma, pancreatic cancer and colorectal cancer, the role of SNHG14 in cardiac disorders has not been illustrated." (PMID 32436661, 2020). "Importantly, the expression level of SNHG14 has been demonstrated correlated with prognosis in patients with NSCLC, HCC, ovarian cancer, retinoblastoma, pancreatic ductal adenocarcinoma, colorectal cancer, cervical cancer, and endometrial cancer." (PMID 34631721, 2021).
gastric cancer (12 papers, 2018 to 2025). A primary or metastatic malignant neoplasm involving the stomach. "The ROC curve analysis based on its expression indicates that SNHG14 has a good diagnostic effect for gastric cancer and can potentially become a diagnostic biomarker." (PMID 40521987, 2025). "We have examined clinical samples and gastric cancer cells and observed that SNHG14 is highly expressed in GC, correlating with poor prognosis." (PMID 40521987, 2025). "For example, SNHG14 promoted cell migration, invasion, proliferation and resistance to cell apoptosis in gastric cancer via miR-145/SOX9 axis." (PMID 33485374, 2021). "Other than that, it is known that SNHG14 depletion strains gastric cancer cell viability, migration, invasion, and contributes to enhanced apoptosis." (PMID 33482820, 2021). "So far, impact of SNHG14 on gastric cancer development has been discovered to constrain cell viability, migration, invasion, and promote cell apoptosis, by serving as a competing endogenous RNA of miR-145." (PMID 31683259, 2019). "Previously, SNHG14 was suggested by several works to pose carcinogenic impact on diverse types of cancers, such as gastric cancer, clear cell renal cell carcinoma, and breast cancer." (PMID 31570691, 2019). "In summary, SNHG14 could be a valuable biomarker and therapeutic target against gastric cancer." (PMID 40521987, 2025). "Therefore, SNHG14 can facilitate the proliferation and metastasis of gastric cancer." (PMID 40521987, 2025). "Moreover, FISH and nuclear‐cytoplasmic fractionation assays conducted on gastric cancer cells indicate that SNHG14 is predominantly localised in the cytoplasm, suggesting that it may exert its oncogenic effects in gastric cancer through post‐translational modifications." (PMID 40521987, 2025). "This study found that PWAR6, LINC00641, SNHG14, and PART1 are markedly downregulated and involved in ferroptosis of gastric cancer." (PMID 36418919, 2022). "Small nucleolar RNA host gene 14 (SNHG14) is documented to elicit oncogenic functions by modulating proliferation, migration, invasion, and conferring chemo-resistance in multiple types of malignancies, such as gastric cancer, clear cell renal cell carcinoma, and breast cancer." (PMID 31570691, 2019).
glioma (12 papers, 2018 to 2025). A benign or malignant brain and spinal cord tumor that arises from glial cells (astrocytes, oligodendrocytes, ependymal cells). "In glioma, the lncRNA SNHG14 is downregulated and destabilized owing to a loss in Lin28A, leading to an increase in IRF6-mediated aerobic glycolysis." (PMID 33126510, 2020). "In cerebral infarction and glioma, the function of SNHG14 has also been reported, suggesting its association with neurological disorders." (PMID 31683259, 2019). "In the present study, we aimed to discover the underlying molecular mechanism of SNHG14 in glioma progression." (PMID 29552296, 2018). "In gliomas, RNA-binding protein lin28A and lncRNA SNHG14 are upregulated, while the transcription factor IRF6 is downregulated." (PMID 38967893, 2024). "For example, upregulation and knockdown of SNHG14 in glioma cells inhibits glycolysis and proliferation." (PMID 37145002, 2023). "In glioma cells, the Lin28A/SNHG14/IRF6 axis is pivotal for the reprogramming of glucose metabolism and the spurring of oncogenesis, and depletion of Lin28A reduced in vivo xenograft tumor outgrowth and prolonged nude mice survival." (PMID 34868981, 2021). "Our results showed that SNHG14 was overexpressed and promoted the Warburg effect in glioma, suggesting that SNHG14 regulates glycometabolism in glioma." (PMID 32527996, 2020). "We analyzed the expression and function of Lin28A, SNHG14, IRF6, GLUT1, and PKM2 and their underlying mechanisms in the tumorigenesis of glioma." (PMID 32527996, 2020). "SNHG14 was overexpressed in glioma tissues as compared to NBTs and further increased with the advancement in the grade of glioma." (PMID 32527996, 2020). "LncRNA microarrays showed that SNHG14 was significantly downregulated in Lin28A-depleted glioma cells." (PMID 32527996, 2020). "Taken together, silencing SNHG14 suppressed glycolysis and proliferation, while promoting apoptosis in glioma cells." (PMID 32527996, 2020). "The schematic cartoon of the mechanism of Lin28A/SNHG14/IRF6 axis functions as a potential aerobic glycolysis enhancer in glioma." (PMID 32527996, 2020). "In summary, the study provides novel insights into the role and function of the Lin28A/SNHG14/IRF6 axis in regulating glycometabolism in human glioma." (PMID 32527996, 2020). "SNHG14 was downregulated in glioma tissues, whereas miR-92a-3p was significantly upregulated in the same paired 29 tumour and NAT samples." (PMID 29552296, 2018). "SNHG14 expression was significantly lower in glioma cell lines (U251 and U87) than that in normal HEB cells." (PMID 29552296, 2018). "Overexpression of SNHG14 markedly repressed cell proliferation and invasion and promoted cellular apoptosis in glioma cell lines." (PMID 29552296, 2018). "Taken together, SNHG14 inhibited cell proliferation and migration and promoted apoptosis by sponging miR-92a-3p in glioma." (PMID 29552296, 2018). "First, we measured the expression levels of SNHG14 in glioma tissues and cell lines and found its downregulation in glioma." (PMID 29552296, 2018). "SNHG14 expression was significantly downregulated in 83% (24/29) of the glioma tissues compared with that in the NATs (p < 0.001)." (PMID 29552296, 2018). "In this study, we aimed to explore the functional involvement of small nucleolar RNA host gene 14 (SNHG14) and its potential regulatory mechanism in glioma progression." (PMID 29552296, 2018). "Because SNHG14 was downregulated in glioma, we evaluated the impact of SNHG14 overexpression in glioma cell lines to explore its biological functions." (PMID 29552296, 2018). "SNHG14 was targeted and inhibited by miR-92a-3p and acted as a tumour-suppressing gene, which inhibited the malignant behaviour of glioma cells." (PMID 29552296, 2018). "In the present study, we identified that SNHG14 was significantly downregulated in glioma tissues and cell lines." (PMID 29552296, 2018).